TRPV1 (transient receptor potential cation channel subfamily V member 1)
Diseases named in the same sentence as TRPV1 in open-access papers (continued):
Sharing a sentence is not in itself a finding about the gene and the disease.
prostatitis (continued). "In our study, we aimed to investigate the functional relationship between SP, NK-1, and TRPV1 in the DRG following prostatitis." (PMID 39544909, 2024). "In our study, we found that SP and TRPV1 protein levels were increased in bladder tissue after prostatitis and were co-expressed in the bladder urothelium." (PMID 39544909, 2024). "The rich TRPV1 sensory innervation found in the human prostate plays an important role in the development of chronic prostatitis (Chronic Prostatitis/Chronic Pelvic Pain Syndrome—CP/CPPS)." (PMID 27322240, 2016). "However, there is a paucity of research examining the therapeutic potential of TRPV1 in the context of prostatitis." (PMID 40070569, 2025). "However, many uncertainties remain regarding the exact mechanism of action and potential therapeutic targets of TRPV1 channels in prostate disease." (PMID 39364048, 2024). "One study discovered a correlation between prostatitis-induced bladder overactivity, alterations in TRPV1 in DRG, and heightened expression of neurogenic substances like NGF in the bladder mucosa with the heightened excitability of bladder afferent nerves triggered by prostatitis." (PMID 39364048, 2024). "We observed that prostatitis rats demonstrated elevated expression of SP and TRPV1 in the bladder." (PMID 39544909, 2024). "Preclinical data using TRPV1 as a drug target for prostatitis." (PMID 39364048, 2024). "However, further in-depth research is necessary to elucidate the precise mechanism of TRPV1 channels in prostate diseases and to formulate appropriate treatment strategies." (PMID 39364048, 2024). "Modulating TRPV1 channels has the potential to alleviate LUTS and pain associated with prostatitis." (PMID 39364048, 2024). "This review provides an overview of the TRPV1 channel structure and explores its expression in prostate tissue and innervation, aiming to understand the role of TRPV1 in pain and LUTS associated with prostatitis." (PMID 39364048, 2024). "Consequently, our study investigates the role of TRPV1 in the progression of prostatitis and evaluates whether desensitization of this channel may serve as a beneficial treatment for alleviating symptoms associated with CP/CPPS." (PMID 40070569, 2025). "Additionally, we assessed the expression of TRPV1 and its related substances within the cross-organ cross-sensitization pathway of prostatitis to gain further insights into the specific mechanism by which RTX may treat chronic prostatitis." (PMID 40070569, 2025). "Consequently, by integrating the pathogenesis of chronic prostatitis with the function of TRPV1 in the sensitization of internal organs, it is crucial to develop TRPV1-targeted drugs that are safe, efficient, and have minimal side effects for the management of prostatitis in the future." (PMID 39364048, 2024). "Although studies have demonstrated that prostatitis can enhance the expression of TRPV1 in dorsal root ganglia (DRG) and contribute to organ sensitization, there is little research investigating the mechanisms underlying sensitization following the upregulation of TRPV1." (PMID 39544909, 2024). "Moreover, downregulation of TRPV1 in urothelial cancers of human bladder was determined and the hypothesis that TRPV1 is involved in differentiation was postulated." (PMID 24868547, 2014). "Consequently, during the progression of chronic prostatitis, alterations in TRPV1 may indirectly or directly influence the sympathetic and parasympathetic nervous systems of the prostate and bladder, thereby exacerbating the development and functional changes associated with chronic prostatitis." (PMID 39364048, 2024). "The protein levels of TRPV1 and BDNF in the L6 DRG/spinal cord were increased in capsaicin-induced prostatitis rats and were downregulated by Li-ESWT." (PMID 35563108, 2022). "Therefore, the presence of numerous TRPV1 sensory nerves in the prostate and bladder suggests a potential new approach for treating pain and LUTS in patients with chronic prostatitis." (PMID 39364048, 2024).
prostatitis (continued). "In summary, inflammatory changes in pathological prostatitis can trigger the activation of TRPV1 channels in both neural and non-neural tissues, as well as sensitize C-fibers." (PMID 39364048, 2024). "This could be attributed to a lack of understanding regarding the pathogenesis of prostatitis and the potential side effects of TRPV1." (PMID 39364048, 2024).
pulmonary fibrosis (6 papers, 2019 to 2022). Chronic progressive interstitial lung disorder characterized by the replacement of the lung tissue by connective tissue, leading to progressive dyspnea, respiratory failure, or right heart failure. "Herein, we hypothesized that the cough reflex increases in a model of bleomycin-induced pulmonary fibrosis in guinea pigs, which is associated with up-expression of TRPV1 and TRPA1." (PMID 30717786, 2019). "However, few studies have examined the association between TRPV1 and pulmonary fibrosis." (PMID 36045746, 2022). "TRPV1 is increased in bleomycin-induced lung fibrosis in guinea pigs and TRP channels in general were suggested to contribute to lung repair processes." (PMID 35212819, 2022). "We have previously shown that expression of TRPA1 and TRPV1 in the lungs of a guinea pig model of bleomycin-induced pulmonary fibrosis was elevated, which was companied with increased cough sensitivity." (PMID 34078339, 2021). "Our previous study also showed that expression of TRPV1/TRPA1 was upregulated in a guinea pig model of bleomycin-induced pulmonary fibrosis with chronic cough." (PMID 34078339, 2021). "Expression of TRPV1/TRPA1 was upregulated in the chronic cough related to bleomycin induced pulmonary fibrosis in guinea pigs, which provided new insights into the mechanism of IPF-associated cough hypersensitivity." (PMID 30717786, 2019). "We have previously also shown that the expression of TRPV1 and TRPA1 increased in the lungs of guinea pigs with bleomycin-induced pulmonary fibrosis." (PMID 34078339, 2021). "However, TRPV1 modulation in experimental lung fibrosis had not been studied before, but our results indicate a beneficial role of CPS via modulation of TRPV1 and restoration of PACS2 protein levels and ER–mito tethering." (PMID 35212819, 2022). "To further address these unknown issues, we aimed to explore the expression of TRPA1 and TRPV1 in the jugular ganglia and nodose ganglia and that of neurogenic indicators such as SP, CGRP, and NK1R in the lungs using an established guinea pig cough model of pulmonary fibrosis induced with bleomycin." (PMID 34078339, 2021).
pulpitis (6 papers, 2013 to 2025). Inflammation of the dental pulp. "Bradykinin is a known upstream activator of TRPV1, further cementing the link between pulpitis-associated pain and TRPV1." (PMID 41516061, 2025). "Pulpitis elevates endogenous TRPV1 and TRPA1 agonists, while inflammatory mediators sensitize TRP channels, amplifying pain." (PMID 41516061, 2025). "For example, both diabetic periodontitis and LPS-induced pulpitis were found to enhance TRPV1 expression in dental sensory neurons." (PMID 41516061, 2025). "The administration of a TRPV1 antagonist into facial skin reduces mechanical hyperalgesia in facial skin following pulpal inflammation, suggesting that ectopic upregulation of TRPV1 in TG can contribute to the ectopic pain under pulpitis conditions." (PMID 41516061, 2025). "LPS treatment in dental trigeminal ganglia induced pulpitis by upregulating expression of the TRPV1 channel." (PMID 32377171, 2020). "Oxidized linoleic acid metabolites generated by cytochrome P450 during pulpitis may function as endogenous TRPV1 agonists, contributing to inflammatory dental pain." (PMID 41516061, 2025). "Of note, lipopolysaccharides (LPS) from Gram (−) bacteria upregulated TRPV1 expression in TG, and Complete Freund’s Adjuvant (CFA) upregulated TRPV1 in TG neurons innervating adjacent teeth, suggesting the potential contribution of TRPV1 to tooth pain under the pulpitis condition." (PMID 31071917, 2019). "In a rat model of acute pulpitis induced by pulp exposure to CFA, increased TRPV1 expression was found in the pulpal afferents." (PMID 41516061, 2025). "Moreover, the overexpression of SIRT6 could inhibit pulpitis by activating the TRPV1 channel." (PMID 35249460, 2022). "Coinciding with the increase in TLR4 we also observed an increase in Trpv1 mRNA expression at 24 hours post injury, similar to increased protein expression found in rats with pulp exposure or CFA-induced pulpitis models." (PMID 32066827, 2020).
renal cell carcinoma (6 papers, 2019 to 2023). "In agreement, low expression of TRPV1 in renal cell carcinoma is associated with poor clinical outcomes." (PMID 37371563, 2023). "In renal cell carcinoma, TRPV1 expression positively correlated with M1-type anti-tumoral macrophages, and negatively correlated with M2-type tumorigenic macrophages." (PMID 37371563, 2023). "For instance, the regulation of immune cells is closely related to the copy number alteration of TRPV1 in renal cell carcinoma." (PMID 36160018, 2022). "On the contrary, in renal cell carcinoma, CPS downregulates PD-L1 expression in a TRPV1-independent manner, suggesting a potential application of CPS as an immune-adjuvant in this type of cancer." (PMID 35681623, 2022). "In contrast, TRPV1 expression levels in high-grade astrocytes, “brain tumors,” U373 cells, and RT4 renal cell carcinoma cells are elevated in comparison to healthy controls." (PMID 32545311, 2020).
temporal lobe epilepsy (6 papers, 2018 to 2024). A localization-related (focal) form of epilepsy characterized by recurrent seizures that arise from foci within the temporal lobe, most commonly from its mesial aspect. "The current study found that GPR55 is upregulated in neurons following THC exposure, while TRPV1 is downregulated in temporal lobe epilepsy." (PMID 38404644, 2024). "Out of our 13 transcripts of interest, TRPV1 was found to be significantly down-regulated in the neocortex of patients with temporal lobe epilepsy." (PMID 38404644, 2024). "TRPV1 expression is enhanced in the hippocampus of rats and the dentate gyrus of mice with temporal lobe epilepsy, as well as in the brains of individuals with temporal lobe epilepsy." (PMID 37744878, 2023). "Indeed, we found a significant downregulation of TRPV1 mRNA in the neocortex of patients with temporal lobe epilepsy compared to control tissues." (PMID 38404644, 2024). "Furthermore, increased expression of TRPV1 has been found in the hippocampus of rats and the dentate gyrus of mice with temporal lobe epilepsy as well as in the cortex of patients with temporal lobe epilepsy." (PMID 33748103, 2021). "Similarly, Bhaskaran and Smith (2010) found an increase in TrpV1 expression in the dentate gyrus of a mouse model of temporal lobe epilepsy." (PMID 30417826, 2018).
uveal melanoma (6 papers, 2018 to 2025). A melanoma derived from melanocytes of the uveal tract. "We found that TRPM8 is also overexpressed in highly malignant retinoblastoma and uveal melanoma along with TRPV1 compared to their levels in healthy human uvea or retina." (PMID 30483120, 2018). "Furthermore, TRPV1 was upregulated in uveal melanoma cells suggesting that TRPM8 is a potential drug target for suppressing VEGF-induced increases in neovascularization and uveal melanoma growth." (PMID 36768856, 2023). "Since TRPs like TRPV1 and TRPM8, as well as NGF receptors (TrkA), are (over)expressed in tumors such as uveal melanoma (UM) or retinoblastoma, we tested NGF on calcium regulation in human UM cells for comparison purposes." (PMID 40422222, 2025). "In several cell lines, including uveal melanoma, endothelial, and corneal epithelial cells, activation of TRPM8 inhibited the VEGF transactivation of TRPV1 and the consequent pro-tumorigenic effects mediated by the VEGFR." (PMID 36768856, 2023). "Functional TRPV1, TRPM8, and TRPA1 were also expressed in malignant human uveal melanoma tissues and cell lines." (PMID 34831352, 2021). "Since the G protein-coupled cannabinoid receptor 1 (CB1) is expressed in uveal melanoma cells, we determined if either this receptor or its coupled G-proteins affect interactions between TRPM8 and TRPV1 in UM cells." (PMID 30483120, 2018). "Previous studies demonstrated the co-expression of TRPV1 with TRPM8 in different cell types including rat hippocampal neurons, intralobar pulmonary arteries, aorta, neuroendocrine tumor cells, retinoblastoma cells, uveal melanoma cells, and corneal cells." (PMID 30298050, 2018).
acute kidney injury (5 papers, 2012 to 2025). Sudden and sustained deterioration of the kidney function characterized by decreased glomerular filtration rate, increased serum creatinine or oliguria. "This study investigated whether capsaicin protects against LPS-induced acute kidney injury through TRPV1/UCP2 axis." (PMID 37528882, 2023). "Stimulation of TRPV1 channels protects against ischemia/reperfusion (I/R)-induced acute kidney injury (AKI)." (PMID 25330307, 2014). "Moreover, discovery of novel pharmacological TRPV1 modulators may be a successful strategy for better treatment of acute kidney failure." (PMID 25330307, 2014). "Since stimulation of transient receptor potential channels of the vanilloid receptor subtype 1 (TRPV1) mitigates acute kidney injury (AKI) and endogenous N-acyl dopamine derivatives are able to activate TRPV1, we tested if synthetic N-octanoyl-dopamine (NOD) activates TRPV1 and if it improves AKI." (PMID 22916273, 2012).
allergic rhinitis (5 papers, 2015 to 2024). Inflammation of the nasal mucous membranes caused by an IgE-mediated response to external allergens. "Additional studies should then be conducted to investigate the role of TRPV1 as a drug target in allergic rhinitis using longer-acting drug formulations." (PMID 39185421, 2024). "During seasonal allergen exposure, patients with allergic rhinitis feature an increased itch response to TRPV1 stimulation." (PMID 39185421, 2024). "The number of TRPV1+ inflammatory cells was significantly higher in subjects with allergic rhinitis, compared with control subjects." (PMID 26700618, 2016). "In TRPV1 knockout allergic rhinitis (AR) mice, eosinophil infiltration, Th2/Th17 cytokines in the nasal mucosa, and total and ova-specific IgE levels in serum decreased, compared with wild-type AR mice." (PMID 26700618, 2016). "T cells are one of the most important players in allergic inflammation, so we aimed to evaluate whether the suppression of TRPV1 could influence allergic inflammation using a mouse model of allergic rhinitis." (PMID 26700618, 2016). "Further research is needed to investigate whether these modulations of TRPV1, produced by acupuncture in the spinal dorsal horn of rats or mice, can also be found in the trigeminal ganglia or nasal mucosa of humans with allergic rhinitis." (PMID 26339274, 2015). "The central importance of TRPV1 in allergic rhinitis raises the question of how acupuncture might modulate TRPV1 either directly or indirectly." (PMID 26339274, 2015). "However, the role of TRPV1 in CD4+ T cell in allergic rhinitis remains poorly understood." (PMID 26700618, 2016). "A proposed model has previously hypothesized that acupuncture might downregulate proinflammatory neuropeptides, proinflammatory cytokines, and neurotrophins, modulating transient receptor potential vallinoid (TRPV1), a G-protein coupled receptor which plays a central role in allergic rhinitis." (PMID 26339274, 2015). "To investigate the role of TRPV1 in the allergic immune response, we compared TRPV1(−/−) and TRPV1(+/+) mice using the OVA-sensitized allergic rhinitis model." (PMID 26700618, 2016). "In double-blinded randomized cross-over studies, the topical intranasal TRPV1 antagonist, SB-705498 did not alleviate allergen-induced or cold dry air-elicited symptoms in allergic or non-allergic rhinitis." (PMID 26700618, 2016). "Until now, the expression and functional role of TRPV1 in immune cells including CD4+ T cells had not been investigated in allergic rhinitis (AR)." (PMID 26700618, 2016). "However, additional studies, using drug formulations with a prolonged duration of action, should be conducted before TRPV1 is ruled out as a drug target in allergic rhinitis." (PMID 27485456, 2016). "Since nasal swelling is more significant clinically in allergic rhinitis than hyperalgesia, signalling pathways identified in hyperalgesia studies which do not involve TRPV1 may be less relevant to acupuncture's effects on allergic rhinitis." (PMID 26339274, 2015).
chronic asthma (5 papers, 2019 to 2023). An asthma that is characterized by the development of persistent airway inflammation and recurrent attacks of breathlessness and wheezing, which vary in severity and frequency. "Treatment directed at TRPV1 significantly alleviated airway hyperresponsiveness, airway inflammation, and remodeling in a chronic asthma murine model, which indicated the TRPV1 receptor can be a potential drug target for chronic bronchial asthma." (PMID 37025492, 2023). "Administration of capsazepine or TRPV1 siRNA attenuated airway inflammation, hypersensitiveness, as well as reduced levels of pro-inflammatory neuropeptides and oxidative stress in mouse model of chronic asthma." (PMID 34681836, 2021). "However, treatment directed at TRPV1 significantly alleviated IL-4, IL-5, and IL-13 level in a chronic asthma murine model, while conversely TRPA1 promoted OVA-induced IL-4 production during acute allergic lung inflammation." (PMID 34099759, 2021). "In contrast, treatment with TRPV1 antagonist capsazepine or TRPV1 siRNA reduced airway hyper-responsiveness (AHR) and airway remodeling with suppressed Th2 cytokines (IL-4, IL-5 and IL-13) and epithelial cell-derived cytokines (TSLP, IL-33, and IL-25) in ovalbumin-induced chronic asthma." (PMID 35634308, 2022).
Dyskinesia (5 papers, 2015 to 2024). A movement disorder which consists of effects including diminished voluntary movements and the presence of involuntary movements. "Lastly, mechanisms facilitated by cannabinoid binding to TRPV1 and possibly other vanilloid receptors are associated with motor responses to levodopa and also suggest TRPV1 as a potential therapeutic target for PD which is devoid of dyskinesia." (PMID 25888232, 2015). "The most probable explanation for these effects came from a study where it was observed that TRPV1 blockade positively regulates the crosstalk between endocannabinoid receptors and TRPV1 downstream signaling which helps prevent L-DOPA induced dyskinesias." (PMID 33330461, 2020). "On the other hand, TRPV1 is suggested to mediate the reducing effects of OEA on levodopa (L-DOPA)-induced dyskinesia." (PMID 30288203, 2018). "Interestingly, oleoylethanolamide (OEA) also augments the effect of AEA by acting on TRPV1; furthermore it decreases LID at doses that do not change motor behavior in the mouse model of dyskinesia." (PMID 25888232, 2015).